TRPV2 (transient receptor potential cation channel subfamily V member 2)
Diseases named in the same sentence as TRPV2 in open-access papers (continued):
Sharing a sentence is not in itself a finding about the gene and the disease.
diabetes (5 papers, 2020 to 2024). "Our data indicate that the diabetes-induced impairment of myogenic tone is related to a complete loss of stretch-dependent TRPV2 current activity on the retinal VSMCs." (PMID 36134661, 2022). "Our findings suggest that loss of stretch-dependent TRPV2 channel activity underlies the impaired myogenic reactivity of retinal arterioles during diabetes." (PMID 36134661, 2022). "The experiments involving TRPV2 heterozygotes indicate, however, that downregulation of TRPV2 expression to levels similar to those seen in diabetes is adequate to explain the loss of the myogenic response and pressure autoregulation in the retina." (PMID 36134661, 2022). "Our data suggest that TRPV2 dysfunction underlies the loss of retinal blood flow autoregulation in diabetes and provide strong support for the hypothesis that autoregulatory deficits are involved in the pathogenesis of DR." (PMID 36134661, 2022). "Mechanistically, this effect of diabetes appears to be mediated, at least in part, through TRPV2 downregulation at the mRNA, protein, and functional levels." (PMID 36134661, 2022). "Collectively, these findings show that diabetes downregulates the molecular and functional expression of TRPV2 channels in retinal VSMCs." (PMID 36134661, 2022). "A clearer knowledge of the mechanisms linking the activation of this channel to membrane stretch will be required to fully understand how diabetes disrupts stretch-dependent TRPV2 current in retinal VSMCs." (PMID 36134661, 2022). "These genes are exemplified by TRPV2 whose changed expression can lead to diabetes, bone disorders, and cardiovascular symptoms." (PMID 32366041, 2020). "Our data, therefore, imply that diabetes may also act to uncouple signaling mechanisms linking membrane stretch to TRPV2 channel activation." (PMID 36134661, 2022).
leukemia (5 papers, 2014 to 2025). A malignant (clonal) hematologic disorder, involving hematopoietic stem cells and characterized by the presence of primitive or atypical myeloid or lymphoid cells in the bone marrow and the blood. "A strong piece of evidence for the involvement of TRPV2 in the pathogenesis of leukemia and associated pulmonary dysfunction comes from our recent study revealing that TRPV2 mRNA transcripts and protein expression profiles are altered in leukemic blasts (LBs)." (PMID 33376561, 2020). "In this study, we took the first steps towards exploring whether TRPV2 can be used as a pharmacodynamic biomarker for leukemia and associated pulmonary inflammation." (PMID 30733502, 2019). "As expected, TL and SKF treatments significantly blunted the kinetics of the fMLP-evoked fast and sustained rise in [Ca2+]i in all leukemia cell lines due to inhibition of fMLP-induced stimulation of TRPV2 Ca2+ activity." (PMID 30733502, 2019). "TL and SKF inhibited chemotactic peptide fMLP-induced response linked to TRPV2 Ca2+ activity, and down-regulated expression of surface marker CD38 involved in leukemia and lung airway inflammation." (PMID 30733502, 2019). "The siRNA and TL experiments indicate that the degree of apoptosis somewhat correlates with the level of f-TRPV2 isoform since the leukemia cell line K562, which has the highest level of f-TRPV2, exhibited slightly more apoptosis than the U937 cell line." (PMID 30733502, 2019). "Thus, strong evidence points toward a role for TRPV2 in the survival and proliferation of LBCs, and these data further support the concept of using TRPV2 as a pharmacodynamic biomarker for leukemia." (PMID 30733502, 2019). "Therefore, TRPV2 merits further exploration as a pharmacodynamic biomarker for leukemia patients (with pulmonary inflammation) who might be suitable for a novel [adjuvant] therapeutic strategy based on TL." (PMID 30733502, 2019). "In parallel, we conducted phagocytosis assays in rat basophilic leukemia (RBL) cells, including a CRISPR/Cas9-generated TRPV2-knockout cell line." (PMID 41511297, 2025). "The analysis of human transcrittoma by GNF gene expression has indicated the expression of TRPV2 channels in CD34+/CD45+/CD133+CD73− haematopoietic stem cells, suggesting a role for these channels in haematopoietic-derived leukaemia and lymphoma tumors." (PMID 24709905, 2014). "We cannot provide a rational explanation for this unexpected differential response but perhaps it is due to a difference in the genetic makeup of the two leukemia cell lines and the fact that THP-1 cells displayed a low level of f-TRPV2, the primary target of TL and SKF." (PMID 30733502, 2019). "Furthermore, TRPV2 expression in CD34+/CD45+/CD133+/CD73+ hematopoietic stem cells, from which all lineages of blood cells are derived, suggests a role for this channel in hematopoietic cell-derived tumors, i.e., leukemias and lymphomas." (PMID 33376561, 2020).
urothelial carcinoma (5 papers, 2019 to 2023). A malignant neoplasm derived from the transitional epithelium of the urinary tract (urinary bladder, ureter, urethra, or renal pelvis). "In fact, f-TRPV2 and s-TRPV2 had opposite trends of expression in urothelial carcinoma tissues when compared to normal bladder specimens." (PMID 33376561, 2020).
Arthritis (4 papers, 2018 to 2024). Inflammation of a joint. "TRPV2 has been previously indirectly implicated in angiogenesis since activation of the channel in fibroblasts by its synthetic cannabinoid agonist (O-1821) was correlated with altered angiogenesis in a mouse model of arthritis." (PMID 31288452, 2019). "In vivo studies unveiled that the presence of this kind of cell at the acupoints and their degranulation contributed to the AP analgesic effect, and TRPV2 knockout arthritis mice had reduced response to AP." (PMID 34073103, 2021). "By synthesizing these findings, it becomes evident that TRPV2 emerges as a multifaceted player in joint health, exerting protective effects in the realm of articular cartilage maintenance and demonstrating regulatory potential in the context of arthritis." (PMID 38540712, 2024). "Further in vivo study unveiled that TRPV2-knockout arthritis mice had reduced response to AP." (PMID 34073103, 2021). "In summary, the current data suggests that agonism of TRPC5, TRPM3, TRPM8, and TRPV2 may help ameliorate or prevent arthritis, while antagonism of TRPM7 and TRPV4 may have a similar effect." (PMID 30326593, 2018).
bladder tumor (4 papers, 2013 to 2025). "In T24 bladder tumor cells, CBD (30 μM) triggered apoptosis, as indicated by annexin V staining +/PI—(11.4%, n = 3), through the influx of Ca2+ via TRPV2 channels." (PMID 40006844, 2025). "TRPV2 activity, which may be mediated by direct matrix metalloproteinase 2 (MMP2) regulation, is important in bladder tumor development and progression." (PMID 24223658, 2013). "Furthermore, TRPV2 activity, which may be mediated by direct MMP2 regulation, is important in bladder tumor development and progression." (PMID 24223658, 2013).
endometriosis (4 papers, 2018 to 2021). The growth of functional endometrial tissue in anatomic sites outside the uterine body. "The functionality of TRPV2 in endometriosis-derived hESC was investigated by using the cannabinoid THC, which revealed a robust increase in intracellular Ca2+ concentration." (PMID 30134548, 2018). "TRPV2, TRPV4, TRPC1/4, and TRPC6 were expressed in hESC samples retrieved from women affected by endometriosis both at the molecular and functional levels." (PMID 32046116, 2020). "Additionally, TRPV2, TRPV4, TRPC1/4, and TRPC6 were found in human endometrial stromal cells (hESCs) from patients with endometriosis." (PMID 34337010, 2021). "Additionally, and in line with previous reports of control patients, TRPV2, TRPV4, TRPC1/4, and TRPC6 were present in human endometrial stromal cells (hESC) from endometriosis patients both at the molecular and functional level." (PMID 30134548, 2018). "TRPV2 functionality was investigated by the application of 50 μM THC, which elicited a robust calcium influx in both endometriosis-derived and control hESC, of 314 ± 73 nM in 36 ± 12% of all cells (total of 171 cells) and 244 ± 42 nM in 56 ± 14% of all cells (n = 314 cells), respectively." (PMID 30134548, 2018). "Moreover, these channels were previously discovered to be somehow involved in several processes that regarded pathogenesis of endometriosis: TRPC1, TRPC4, and TRPV2 are involved in cell migration; TRPC4 in cell adhesion; and TRPM4, TRPM7, and TRPV2 have a crucial role in cell proliferation." (PMID 32046116, 2020).
ischemic stroke (4 papers, 2020 to 2025). A stroke disorder caused by obstruction of blood flow to the brain, due to thrombotic (local blood clot formation) or embolic (due to a blood clot or other material traveling from another site) event. "Few studies focused on the involvement of TRPV2 in preserving BBB integrity in ischemic stroke." (PMID 33806707, 2021). "Altogether, these results suggest that activating TRPV2 might be a relevant strategy to positively modulate the BBB in the context of brain disorders including ischemic stroke." (PMID 33262985, 2020). "TRPV1 or TRPV4 inhibition has been applied in treating ischemic stroke via preserving the BBB permeability in various in vitro and/or in vivo experiments, while TRPV2, the most expressed isoform in human BBB, is much less studied." (PMID 33806707, 2021). "TRPM2, TRPV2, and TRPV4 exacerbate neuroinflammation and worsen outcomes in ischemic stroke." (PMID 41399206, 2025). "TRPM2, TRPV2, and TRPV4 exacerbate ischemic stroke, while TRPM8 plays a protective role." (PMID 41399206, 2025). "TRPV2 is evidenced to play a main role in regulating the human BBB permeability, which enables the potential participation of TRPV channels in treating BBB dysfunction related to brain diseases, including, but not limited to, ischemic stroke." (PMID 33806707, 2021).
non-small cell lung carcinoma (4 papers, 2018 to 2022). A group of at least three distinct histological types of lung cancer, including non-small cell squamous cell carcinoma, adenocarcinoma, and large cell carcinoma. "The Cancer Cell Line Encyclopedia (CCLE) database shows that TRPV2 expression is higher in MM cell lines, compared to other cancer cell lines, such as non-small cell lung carcinoma cells and neuroblastoma cells." (PMID 30326911, 2018).
prostate tumors (4 papers, 2013 to 2021). "Upregulation of TRPV2 levels has been associated with human prostate tumor-derived endothelial cell proliferation." (PMID 32344908, 2020). "TRPV2 is expressed in several cell types and is required for directional migration of macrophages, prostate tumours, bladder cancer and oesophageal squamous cell carcinoma." (PMID 33994356, 2021). "Further it was shown that siRNA- mediated TRPV2 silencing reduces the size and invasive properties of xenografted prostate tumors in nude mice and downregulates the expression of MMP2, MMP9 and cathepsin B52, suggesting that TRPV2 is a viable pro-metastatic target in vivo." (PMID 24204345, 2013). "Silencing of TRPV2 by small interfering RNA diminishes the expression of degrading enzymes MMP2, MMP9, and cathepsin B and decreases the formation of metastasis in PC3 prostate tumours established in mice xenografts and bladder tumour development and progression." (PMID 33994356, 2021).
squamous cell carcinoma (4 papers, 2019 to 2022). A carcinoma arising from squamous epithelial cells. "We have found that TRPV2 is more highly expressed in lung adenocarcinomas compared to squamous cell carcinomas." (PMID 35267489, 2022).
acute myeloid leukemia (3 papers, 2014 to 2022). Acute myeloid leukemia (AML) is a group of neoplasms arising from precursor cells committed to the myeloid cell-line differentiation. "The involvement of TRPV2 and Akt kinase was associated with the transcription of acute myeloid leukaemia." (PMID 36497400, 2022). "In addition, TRPV2 down-regulation has been described in acute myeloid leukemia and myelodisplastic syndrome (AML/MDS) patients." (PMID 24709905, 2014).
basal cell carcinoma (3 papers, 2019 to 2022). A carcinoma involving the basal cells. "Moreover, microarray analysis demonstrated that TRPV2 silencing caused downregulation of WNT/β-catenin signaling-related genes and basal cell carcinoma signaling-related genes." (PMID 33376561, 2020). "A pathway analysis of microarray data showed that TRPV2 depletion down-regulated WNT/β-catenin signaling-related genes and basal cell carcinoma signaling-related genes." (PMID 31690728, 2019). "Furthermore, we performed a pathway analysis to clarify the role of TRPV2 in the cancer signaling of ESCC, and revealed that the depletion of TRPV2 down-regulated “basal cell carcinoma signaling”." (PMID 31690728, 2019). "Microarray results showed that TRPV2 markedly affected the expression of genes related to WNT/β-catenin signaling, basal cell carcinoma signaling (cross talk between the hedgehog and WNT/β-catenin pathways), and regulation of the epithelial-mesenchymal transition pathway." (PMID 31690728, 2019). "The role of TRPV2 in skin cancer remains uncertain since staining and semiquantitative analysis of skin samples taken from patients suffering from squamous cell carcinoma (SCC) or basal cell carcinoma (BCC) do not show a significant difference in protein in atypical keratinocytes." (PMID 33376561, 2020).
bladder (3 papers, 2014 to 2019). "In both these urogenital cancers, basal and agonist-induced activity of TRPV2 increased the migratory potential of cancer cells." (PMID 31288452, 2019). "Although TRPV2 cytoplasmic expression in carcinoma cells varied widely between each ESCC sample, we initially evaluated TRPV2 signal intensities in cancer cells as no, weak, and strong expression; the proportion of each intensity in tumors was subsequently measured." (PMID 31690728, 2019).
breast tumors (3 papers, 2016 to 2024). "Overall, these data indicate that TRPV2 plays a role in promoting the growth of xenograft breast tumors through the activation of autophagy." (PMID 39334351, 2024). "When TRPV2 channel stimulation is coupled with chemotherapy, the outcome is a reduction in breast tumor growth as recently demonstrated." (PMID 33376561, 2020). "A puzzling finding in this study is that a large panel of human breast tumors was tested positive for LL-37 expression and correlated with TRPV2 protein expression." (PMID 33376561, 2020). "In a panel of human breast tumors, the expression of TRPV2 and LL-37 was found to be positively correlated." (PMID 26993604, 2016). "Our immunohistochemical studies on breast tumors show a significant correlation of LL-37 and TRPV2 expression indicating a physiological relevance of their cooperation." (PMID 26993604, 2016). "Moreover, the knockdown of TRPV2 in xenograft breast tumors led to the suppression of autophagy, as evidenced by evaluated SQSTM1 levels and decreased expression of ATG5 and LC3." (PMID 39334351, 2024). "‘Transgenic expression of hCAP18/LL-37 in MCF7 cells increased TRPV2 by a posttranscriptional mechanism, which may explain why both were found coexpressed in breast tumors." (PMID 26993604, 2016).
ischemia (3 papers, 2021 to 2024). A hypoperfusion of the BLOOD through an organ or tissue caused by a PATHOLOGIC CONSTRICTION or obstruction of its BLOOD VESSELS, or an absence of BLOOD CIRCULATION. "CBD showed neuroprotective effects, mediated, at least in part, by TRPV2 channels, since the TRPV2 antagonist tranilast blocked them, while THC worsened the neurodegeneration caused by ischemia." (PMID 36292998, 2022). "In this and other works, we have also demonstrated that THC has negative effects on neuronal survival after ischemia, and THC does not show any of the effects seen after CBD administration on the TRPV2 channel, microglia phagocytosis, or rod cell formation." (PMID 36292998, 2022).
metastatic disease (3 papers, 2021 to 2023). "Additionally, our results demonstrated significant correlations between TRPV2 gene expression and several mesenchymal markers in primary and metastatic tumor biopsies, suggesting the channels’ association with the mesenchymal cell phenotype." (PMID 34936030, 2021). "TRPV2-positive cases had particularly dismal prognoses; over half of the patients died within one year of the diagnosis with metastatic disease." (PMID 37240443, 2023). "Overall, TRPV2 expression has been found deregulated in patients with advanced metastatic disease compared to primary solid tumors." (PMID 36744297, 2023). "Accordingly, no TRPV2 expression was observed in pT2 tumors; TRPV2 occurred only in advanced tumors with metastatic disease." (PMID 37240443, 2023).
neuroblastoma (3 papers, 2018 to 2026). Neuroblastoma (NB) is the most common solid, extracranial childhood tumor. "In primary SGN cultures, TRPV2 overexpression aggravated oxidative stress, whereas TRPV2 knockdown in SH-SY5Y cells (a human neuroblastoma cell line) markedly mitigated the oxidative injury as reflected by reduced 4-HNE." (PMID 41792750, 2026). "In addition, we explored the effect of overexpressed flotinllin-1 on TRPV2 protein expression in ND7/23 cells, a hybridization line of mouse neuroblastoma and rat DRG neuron, that express endogenous TRPV2." (PMID 33634132, 2021).
Obesity (3 papers, 2020 to 2021). Accumulation of substantial excess body fat. "Complementary targeted experiments including the modulation of TRPV activation and in particular TRPV2 could confirm the mechanism involved and provide a potential strategy to modulate obesity and related disorders." (PMID 32902117, 2020). "Therefore, the roles of TRPM7 and TRPV2 in the regulation of adipocyte differentiation and obesity might involve a cellular distention mechanism." (PMID 33195411, 2020). "We have previously reported that Trpv1 and Trpv3 mRNAs were significantly decreased, whereas Trpv2 and Trpv4 mRNAs were significantly increased in the white adipose tissue (WAT) of either db/db or diet-induced obesity (DIO) mice." (PMID 33195411, 2020).
osteoarthritis (3 papers, 2021 to 2024). A noninflammatory degenerative joint disease occurring chiefly in older persons, characterized by degeneration of the articular cartilage, hypertrophy of bone at the margins and changes in the synovial membrane. "Several of these genes (MPST, TRPV2) were reported to protect against cartilage calcification in in vivo models of surgically induced osteoarthritis." (PMID 38173036, 2024). "Furthermore, it proposes the potential of TRPV2 as a viable target for innovative approaches to osteoarthritis treatment." (PMID 38540712, 2024). "Therefore, exploring the expression and role of TRPV2 in osteoarthritis will elucidate the molecular mechanism of osteoarthritis." (PMID 38540712, 2024). "The exception was represented by patient 6, in whom the expression of TRPV4 and TRPM8 channels was similar to control tissue and TRPA1, TRPV1, and TRPV2 were expressed, although at a lower level, also in the tissue used as control (probably due to an initial degree of osteoarthritis in this tissue)." (PMID 32955611, 2021). "TRPV2, a mechanosensitive Ca2+ channel, and MPST, a sulfurtransferase that generates the gasotransmitter H2S, are protective against cartilage degradation and calcification in in vivo models of surgically induced osteoarthritis." (PMID 38173036, 2024).